PON1 (paraoxonase 1)
Diseases named in the same sentence as PON1 in open-access papers (continued):
Sharing a sentence is not in itself a finding about the gene and the disease.
glioma (8 papers, 2007 to 2023). A benign or malignant brain and spinal cord tumor that arises from glial cells (astrocytes, oligodendrocytes, ependymal cells). "A similar study evaluated the PON-1 Q192R polymorphism expression in high-grade gliomas and meningiomas." (PMID 37108044, 2023). "We substantiated the idea of TERT and LEP being the risk factors, and LEP and PON1 as protective factors, affecting the immune cell infiltration level and the levels of proinflammatory factors in glioma." (PMID 34114970, 2021). "Interestingly, a polymorphism in the PON1 gene promoter region (108 C > T) was implicated in a study of glioma conducted in Mexico; this PON1 allele is more frequent in Hispanics compared with whites." (PMID 32211584, 2020). "Studies have found that the serum level of PON1 in glioma patients is lower than that of normal people." (PMID 37208656, 2023). "Overall, the results showed that PON-1 serum levels were lower in glioma and meningioma cases than in controls." (PMID 37108044, 2023). "Consensus clustering analysis was used to sort glioma samples into two clusters according to the expression profile of four survival-associated AGs (TERT, LEP, PON1, and SSTR3)." (PMID 34114970, 2021). "We examined 16 single nucleotide polymorphisms (SNPs) of 9 antioxidant genes (GPX1, CAT, PON1, NQO1, SOD2/MnSOD, SOD3, and NOS1*2*3) in 384 glioma and 384 control cases in a Chinese hospital-based case–control study." (PMID 23259684, 2012). "Moreover, the PON enzyme coded by PON1 could detoxify liquid peroxidation, suggesting that PON1 may be the resistance factor of glioma." (PMID 37208656, 2023). "In this study, PON-1 expression was reduced in brain tumor patients compared to non-cancer patients (p < 0.001), but PON-1 serum levels were similar across gliomas and meningiomas." (PMID 37108044, 2023). "The four selected AGs (LEP, TERT, PON1, and SSTR3) were concluded to have important functions in immune cell infiltration of glioma." (PMID 34114970, 2021). "A prognostic risk model was constructed according to four selected AGs (LEP, TERT, PON1, and SSTR3) in the TCGA dataset and Chinese Glioma Genome Atlas (CGGA) database." (PMID 34114970, 2021). "Forty-two high-grade gliomas and forty-two meningiomas were compared to fifty non-cancer control subjects for their serum PON-1 activity." (PMID 37108044, 2023). "The molecular mechanisms of PON1 and SSTR3 in glioma remained ambiguous." (PMID 34114970, 2021). "Our results revealed the expression of PON1 was crucially positive associated with SSTR3 in glioma, while there were a crucial negative association between the expression of PON1 and TERT, and the expression of LEP was negatively associated with PON1 and SSTR3." (PMID 34114970, 2021).
Infertility (8 papers, 2017 to 2025). "In humans, while low levels of PON1 activity have been related to an increase in OS and infertility, high levels of this enzyme have been positively associated with some sperm quality parameters such as concentration, motility, and morphology." (PMID 35204299, 2022). "Reduced PON1 activity was observed in the seminal plasma of men presenting teratozoospermia, azoospermia, subfertility and infertility, whereas increased PON1 activity was positively associated with sperm concentration." (PMID 36156884, 2022). "This study aimed to evaluate serum fetuin-A and PON-1 levels in infertile PCOS women based on body mass index (BMI)." (PMID 34754696, 2021). "The present study aimed to evaluate serum fetuin-A and PON-1 levels as possible markers in infertile women with PCOS based on body mass index (BMI)." (PMID 34754696, 2021). "The area under the curve (AUC) values for five proteins depicted that PON1 had AUC values of 0.97 and 0.80 in predicting AMA infertility and the efficacy of TCM, respectively." (PMID 41141348, 2025).
liver cirrhosis (8 papers, 2010 to 2023). "Their study results indicated that the protein expression of PON1 was reduced by half in both liver cirrhosis and HCC." (PMID 37908943, 2023). "The increasing in PON-1 hepatic expression in chronic hepatitis and liver cirrhosis, probably as a response to the enhanced oxidative stress observed in the earliest stages of these diseases." (PMID 23773725, 2013). "The study was performed in samples from five patients with advanced liver cirrhosis and with preserved renal function, chosen on the basis of having low serum PON1 activity and high serum PON1 concentration." (PMID 20470383, 2010). "Interestingly, the levels of fucosylation and sialylation of PON1 increased significantly in liver cirrhosis, and this increase was even more dramatic in early HCC." (PMID 37908943, 2023). "PON1 may also be a risk factor for chronic hepatitis B, and glycan differences in serum PON1 may serve as potential biomarkers to distinguish early HCC from liver cirrhosis." (PMID 32076459, 2020). "PON1 is considered as a biomarker for the clinical diagnosis of early HCC and able to distinguish early HCC from liver cirrhosis patients with low AFP levels." (PMID 33495404, 2021).
multiple sclerosis (8 papers, 2017 to 2022). A progressive autoimmune disorder affecting the central nervous system resulting in demyelination. "In a small study with 27 individuals with multiple sclerosis that received an isocaloric and ketogenic Mediterranean diet for 4 months it was observed an increase in PON1 activity." (PMID 33374313, 2020). "In recent years, studies have also confirmed that PON1 is involved in the pathogenesis of amyotrophic lateral sclerosis (ALS) and multiple sclerosis (MS)." (PMID 33628379, 2021).
Nephropathy (8 papers, 2012 to 2025). A nonspecific term referring to disease or damage of the kidneys. "In diabetic patients with nephropathy, PON1 activity was negatively correlated with the oxidative stress marker malondialdehyde (MDA), but not with the disease duration and glycemic status." (PMID 38982880, 2024). "Quercetin and cathechins enhanced antioxidant defenses—superoxide dismutase and PON1 activities, reducing oxidative damage suggesting that PON1 mediates the protective effects of flavonoids against kidney damage by oxidative stress." (PMID 22523692, 2012). "Moreover, in conditions such as nephropathy and Crohn’s disease, PON-1’s levels have been shown to correlate with the severity of oxidative stress and inflammation, further supporting its role as a long-term biomarker." (PMID 39765802, 2024). "It was observed that diabetic patients with or without nephropathy, who received atorvastatin for 12 weeks, had significantly higher levels of PON1 activity at the end of the treatment than before treatment." (PMID 38982880, 2024). "This may reflect previous findings that reported comparable PON-1 activity between subjects with T2DM without nephropathy compared to nondiabetic controls, while individuals with T2DM and incipient or overt nephropathy had decreased PON-1." (PMID 28596970, 2017).
unstable angina (8 papers, 2012 to 2024). "Another recently published study, which measured the levels of the enzymes in question, showed that plasma MPO concentrations show a significant inverse correlation with PON-1 levels in patients with stable and unstable angina." (PMID 36463116, 2022). "Relative intensity of apoA-I glycation and activities of high-density lipoprotein (HDL)-associated PON1 and PON3 were determined in 205 consecutive T2DM patients with stable angina with (n = 144) or without (n = 61) significant CAD (luminal diameter stenosis ≥ 70 %)." (PMID 25964115, 2015).
brain tumor (7 papers, 2005 to 2023). "A second study also evaluated the oxidative response from PON-1 polymorphisms and its effect on adult brain tumor development." (PMID 37108044, 2023). "Published evidences make it difficult to determine a priori which PON1 isoform represents a risk factor for the development of brain tumors." (PMID 20723250, 2010). "This study moved on to confirm the effects of PON1 on a larger cohort (201 people) and also showed associationswith the risk of brain tumor developmentfor two other detoxification genes involved in insecticide metabolism, FMO1 (C9536A) and BCHE (A539T)." (PMID 22649665, 2010). "Also, it was investigated that children, when exposed to insecticides, were more likely to develop brain tumors if they also carried PON1C-108T SNP (single nucleotide polymorphism of the paraoxonase—PON1 gene)." (PMID 34943292, 2021). "PON1 genotype and allelic variants of patients with brain tumor (BT) and healthy volunteers." (PMID 20723250, 2010). "PON1 genotype and allelic variants of patients with different types of brain tumor." (PMID 20723250, 2010). "And hence it is conceivable that changes in PON1 activity due to nonsynonymous polymorphisms may modulate the risk to develop brain tumors." (PMID 20723250, 2010). "Little research exists on the relationship between PON-1 and brain tumors." (PMID 37108044, 2023). "Even considering this limitation, this study indicates the absence of a major association of the nonsynonymous PON1 polymorphisms studied with brain tumors." (PMID 20723250, 2010). "Aiming to identify genetic variations related to the risk of developing brain tumors, we investigated the putative association between common nonsynonymous PON1 polymorphisms and the risk of developing astrocytoma and meningioma." (PMID 20723250, 2010). "Seventy one consecutive patients with brain tumors (43 with astrocytoma grade II/III and 28 with meningioma) with ages ranging 21 to 76 years, and 220 healthy controls subjects were analyzed for the frequency of the nonsynonymous PON1 genotypes L55M rs854560 and Q192R rs662." (PMID 20723250, 2010).
carotid atherosclerosis (7 papers, 2014 to 2024). A thickening and loss of elasticity of the walls of carotid arteries that occur with formation of atherosclerotic plaques. "PON 1 activity is decreased in patients with carotid atherosclerosis and cerebral atherosclerosis, and a decreased level of PON 1 is associated with cerebral stroke." (PMID 35801004, 2022). "Additionally, in patients with nasopharyngeal carcinoma, the combination of PON1 rs662 and another polymorphism, rs705379 (c.-108C>T) was associated with carotid atherosclerosis after RT of the neck, while PON1 rs854560 was not investigated." (PMID 33425072, 2020). "PON1 is one of the important enzymes for hydrolyzing LDL oxidation, playing a pivotal role against carotid atherosclerosis." (PMID 25880731, 2015).
Cirrhosis (7 papers, 2010 to 2025). A chronic disorder of the liver in which liver tissue becomes scarred and is partially replaced by regenerative nodules and fibrotic tissue resulting in loss of liver function. "Studies have shown that PON1, which is mainly synthesized by the liver, has a protective effect on oxidative stress against oxidative phosphatase, is associated with the severity of liver damage, and plays a vital role in the development of chronic liver disease into cirrhosis or HCC." (PMID 35892599, 2022). "Moreover, HAN253WTLTPLK (H5N4S2) and (H5N4S1) of PON1 could be served as potential diagnostic indicators for distinguishing AFP-negative HCC from cirrhosis." (PMID 33889548, 2021). "Multiple researches showed that PON1 exhibits a strong diagnostic potential in distinguishing alpha-fetoprotein (AFP)-negative LIHC patients from those with AFP cirrhosis." (PMID 40662145, 2025). "Variations in PON1 glycosylation may be associated with AFP-negative HCC and might be helpful to serve as potential glycomic-based biomarkers to distinguish AFP-negative HCC from cirrhosis." (PMID 33889548, 2021). "There was no significant change in PON1 activity in cirrhosis, leptospirosis and left ventricular failure patients, but there was a significant decrease in HDL-C levels in these patients." (PMID 20339175, 2010). "Cao found that variations in PON1 glycosylation may help to distinguish AFP negative HCC from cirrhosis." (PMID 35126478, 2022). "In addition, the reactivity of PON1 with LCA in HCC patients with negative AFP was significantly elevated than that in cirrhosis patients." (PMID 33889548, 2021).
preeclampsia (7 papers, 2012 to 2025). Preeclampsia is a hypertensive disorder of pregnancy that is characterized by new-onset hypertension with proteinuria presenting after 20 weeks of gestation, and depending on mild or severe forms may initially present with severe headache, visual disturbances, and hyperreflexia. "Further supporting the importance of PON1, it was supported that impaired HDL cholesterol efflux and PON1 activity in cord blood, along with increased maternal PON1 and apoM levels early in pregnancy, are associated with the risk of gestational hypertension." (PMID 39857440, 2025). "While some authors claimed that PON1 activity is reduced in preeclampsia and suggested that this contributes to the development of the disease, others demonstrated higher serum PON1 activity in preeclampsia when compared to uncomplicated pregnancies." (PMID 37511116, 2023). "In contrast, it has been reported that patients with severe preeclampsia and those presenting with clinical symptoms have significantly lower PON-1." (PMID 37627485, 2023). "Preeclampsia patients have moreover exhibited elevated levels of PON-1 during mid-pregnancy, this apparently representing a protective mechanism against the potentially harmful impact of high OS seen in this syndrome." (PMID 37627485, 2023). "It is generally accepted that PON1 activity increases throughout pregnancy; however, results regarding PON1 activity in preeclampsia are rather controversial." (PMID 37511116, 2023). "HDL of mothers diagnosed with preeclampsia showed an increased particle diameter and reduced PON1 activity and was less effective in reducing adhesion molecule expression on endothelial cells." (PMID 36670930, 2022). "In preeclampsia regarding our results, the potential role of PON 1 activity on fetal growth can be explained by further studies." (PMID 23606795, 2013). "In contrast, other studies have observed considerably decreased PON 1 in the presence of clinical symptoms and in patients with severe preeclampsia." (PMID 22748101, 2012). "The serum PON1 activity is probably important in the inhibition of OxLDL in preeclampsia." (PMID 23606795, 2013). "The results of our study were compatible with those of Yaghmaei and Baker and suggested that elevated serum PON1 activity in preeclampsia might be important in the in vivo inhibition of OxLDL." (PMID 23606795, 2013). "Paraoxonase-1 has also been measured to be increased in patients in mid-gestation, possibly in an attempt to shield against the toxic effects of high OS encountered in preeclampsia." (PMID 22748101, 2012).
renal failure (7 papers, 2012 to 2025). "In this review we summarize the findings from the literature and our own laboratory on the decreased PON1 activity in renal failure, the mechanisms proposed and the effect of interventions." (PMID 22523692, 2012). "PON1 activity was significantly lower both in hyperlipidemic and renal failure patients as compared with controls." (PMID 22523692, 2012). "The standardized PON1 activity (paraoxonase/HDL ratio) was also lower in the renal failure patients as compared with hyperlipidemic patients and controls." (PMID 22523692, 2012). "The same group then reported that PON1 in renal failure patients is better activated by salt than that of control subjects, suggesting qualitative changes in the molecule." (PMID 22523692, 2012). "In this paper, we summarize the findings from the literature and our own laboratory on the decreased PON1 activity in renal failure, the mechanisms proposed, and the effect of interventions." (PMID 22523692, 2012). "In patients with kidney failure (KF), on the contrary, PON1 activity was higher." (PMID 30886652, 2019). "In the past decade, much progress has been made on PON1 status in patients with renal failure." (PMID 22523692, 2012). "Results from the multiple case-control studies reported in this paper provide substantial evidence that renal failure is associated with deficient PON1 activity and mass that are independent of changes in HDL-C." (PMID 22523692, 2012). "Renal failure patients share lower PON1 levels and high serum acrolein levels." (PMID 22523692, 2012).
amyotrophic lateral sclerosis (6 papers, 2017 to 2024). Amyotrophic lateral sclerosis (ALS) is a neurodegenerative disease characterized by progressive muscular paralysis reflecting degeneration of motor neurons in the primary motor cortex, corticospinal tracts, brainstem and spinal cord. "Although PON1 has not been associated with bvFTD, it has been linked to amyotrophic lateral sclerosis (ALS), which is in the same disease continuum with FTD." (PMID 30487733, 2018).
chronic obstructive pulmonary disease (6 papers, 2017 to 2026). A chronic and progressive lung disorder characterized by the loss of elasticity of the bronchial tree and the air sacs, destruction of the air sacs wall, thickening of the bronchial wall, and mucous accumulation in the bronchial tree. "The role of PON1 in lung disease remains largely unclear, although some studies have suggested a possible protective role in chronic obstructive lung disease, and inflammatory pulmonary disease related to mustard gas exposure." (PMID 36138190, 2023). "A recent meta-analysis has shown that the POase and AREase activities of PON1 are decreased among patients suffering from chronic obstructive pulmonary disease (COPD) when compared to healthy control group." (PMID 36833509, 2023).
diabetic nephropathy (6 papers, 2021 to 2025). "We also observed a trend of association between PON1 rs622 AG/GG genotype and higher risk for diabetic nephropathy." (PMID 38084238, 2023). "The association of PON1 rs662 with atherogenic dyslipidaemia (P = 0.018) persisted in multiple regression analysis including age (P = 0.974), male gender (P = 0.641), diabetic nephropathy (P = 0.327), and lipid-modifying treatment (P = 0.002)." (PMID 33762698, 2021). "Associations between PON1 SNVs and serum lipid parameters or dyslipidaemic profiles were evaluated among possible confounding variables like age, gender, diabetic nephropathy, and lipid-modifying treatment." (PMID 33762698, 2021). "In this context, there has been increasing interest in determining whether polymorphisms of PON1 gene also contribute to the development of diabetic nephropathy (DN)." (PMID 38982880, 2024). "Furthermore, in diabetic nephropathy alleles -162 A and -1074 G as well as the 54 LL genotype, all associated with the lower PON1 activity, contributed to significantly higher urinary albumin loss." (PMID 33670025, 2021). "In patients with T2DM, PON1 alleles 54L, -162 A and -1074 G, which lead to the lower PON1 activity, were significantly associated with the higher urinary albumin loss indicating the diabetic nephropathy." (PMID 33670025, 2021). "Elevated PON1 levels mitigated oxidative stress and inhibited cell death,thereby promoting cell growth and alleviating diabetic nephropathy throughactivation of the PPARγ signaling pathway." (PMID 40834279, 2025). "PON1, the targeted gene in diabetic nephropathy, was significantlydownregulated in high glucose-induced cells." (PMID 40834279, 2025).